VDAC1 (voltage dependent anion channel 1)
Diseases named in the same sentence as VDAC1 in open-access papers (continued):
Sharing a sentence is not in itself a finding about the gene and the disease.
tumor (continued). "This study provides a rationale for investigating VDAC1 as a therapeutic target in both normoxic and hypoxic tissues with tumor characteristics." (PMID 26322231, 2015). "We next checked the difference in expression levels of genes interacting with VDAC1 between normal and tumor tissues." (PMID 25333947, 2014). "These include controlling energy and metabolic homeostasis, as well as preventing VDAC1-mediated Cyto c release and shielding VDAC1 from pro-apoptotic factor binding, thus offering the tumor cell protection from cell death in a synergic manner." (PMID 23233904, 2012). "In addition, VDAC1 perturbation reduced immunosuppressive cytokine output, suggesting a tumor-intrinsic connection between mitochondrial metabolic regulation and immune-related programs." (PMID 42111501, 2026). "Similarly, in cervical cancer CSCs, Erastin-mediated VDAC1 modulation resulted in elevated ROS levels, leading to apoptotic cell death and decreased tumor growth in in vivo models." (PMID 40608151, 2025). "Similarly, silencing the expression of VDAC1, a mitochondrial protein, has been found to induce metabolic rewiring, promoting differentiation and inhibiting tumor growth." (PMID 39937004, 2025). "Through direct manipulation of ATP generation and promotion of apoptosis, VDAC1 inhibitors show promising results in their ability to inhibit tumor cell proliferation, proving potential for replacing several anticancer drugs that separately target angiogenesis, proliferation, or metabolism." (PMID 41450919, 2025). "HK2 is present in the outer mitochondrial membrane with voltage-dependent anion channel 1 (VDAC1), where it can access the newly synthesized ATP and regulate the tumor cell glucose metabolism, supporting cell proliferation, migration and resistance to apoptosis." (PMID 38529190, 2024). "Additionally, si-VDAC1 treatment resulted in modifications to the TME, including decreased angiogenesis, changes in the extracellular matrix (ECM), reduced tumor-associated macrophages, and inhibited stemness and EMT." (PMID 39456237, 2024). "By influencing metabolism and apoptosis, VDAC1 may participate in tumor cells’ adaptation to the IL-17-induced inflammatory milieu, potentially advancing tumor progression and facilitating immune evasion." (PMID 39835122, 2024). "The mechanism of action is that when VDAC1 is downregulated in tumor cells, it leads to a decrease in mitochondrial membrane potential and adenosine triphosphate (ATP) levels, disrupting the exchange of substances between mitochondria and the cytoplasm, thereby inducing apoptosis." (PMID 38989148, 2024). "Additionally, we demonstrated that the VDAC1-based peptide inhibited tumor development in urethane-induced lung tumors." (PMID 39272828, 2024). "In GBM, silencing VDAC1 led to significant changes in tumor characteristics." (PMID 39456237, 2024). "Additionally, a VDAC1-based peptide inhibited tumor growth, and decreased expression of metabolism-related enzymes and of CSCs markers." (PMID 39272828, 2024). "For instance, studies have reported increased VDAC1 expression may drive dysregulated anti-tumor immunity, and silencing of VDAC could help reprogramming tumor microenvironment." (PMID 38609378, 2024). "Additionally, VDAC1 depletion alters the tumor microenvironment by reducing angiogenesis and modifying the expression of extracellular matrix- and structure-related genes, such as collagens and glycoproteins." (PMID 39456237, 2024). "Additionally, treatment with a peptide derived from VDAC1 also inhibited tumor growth and decreased CSC markers." (PMID 39272828, 2024). "The expression levels of VDAC1 were analyzed in tumor protein extract and fixed sections." (PMID 38607066, 2024). "Indeed, the expression pattern of VDAC1 gene in tumours revealed that AML is the only type in which this gene is exclusively downregulated." (PMID 37344914, 2023).
tumor (continued). "Additionally, the downregulation of VDAC1 in glioblastoma models leads to an inhibition of tumor growth and reversion of malignity markers." (PMID 38139462, 2023). "VDAC1 was highly expressed in most tumor tissues and could serve as a potential biomarker for prognostic diagnosis." (PMID 35958281, 2022). "Our study revealed that VDAC1 might inhibit tumor immunity and might be a novel therapeutic target in BC." (PMID 35729567, 2022). "Next, we analyzed the correlation between TMB/MSI and VDAC1 expression in all tumor types of TCGA." (PMID 35958281, 2022). "Next, VDAC1 expression in the BRCA tumor stages was further analyzed." (PMID 36042412, 2022). "The genetic alteration of VDAC1 was observed in tumor samples in TCGA cohorts." (PMID 35958281, 2022). "MicroRNA-7 may bind to the 3′non-coding region of VDAC1 mRNA to promote tumor cell proliferation and invasion." (PMID 35686107, 2022). "Our study revealed that VDAC1 might inhibit tumor immunity and might be served as a novel therapeutic target in BC." (PMID 35729567, 2022). "Overexpression of VDAC1 in many types of tumors may be involved in some activities of tumor cells with active metabolism and high energy consumption." (PMID 35686107, 2022). "Moreover, SIRT3 is a positive regulator of autophagy and can activate mitochondrial autophagy in tumor cells by promoting the interaction of the voltage-dependent anion channel 1 (VDAC1) with Parkin, a target of mitophagy." (PMID 33815878, 2021). "The glycolysis level of tumor cells is increased, suggesting that VDAC1 knockdown may inhibit tumor growth by inhibiting cell metabolism." (PMID 34539973, 2021). "VDAC1 has been found to be involved in tumor proliferation, migration, metastasis, and invasion." (PMID 33680287, 2021). "Therefore, IHC was performed on the OE and EV7 derived tumours for VDAC1, a mitochondrial voltage dependant anion channel, used here as a surrogate measure for mitochondrial mass." (PMID 33654198, 2021). "In this study, we investigated whether the effects of VDAC1 depletion on tumor cells are mediated via a metabolism–epigenetics axis." (PMID 32331482, 2020). "Our data describe i) a new mechanism for the control of ciliogenesis that is driven by VDAC1-ΔC, the form of VDAC1 that is produced in hypoxia and ii) a new group of ccRCC patients in which the primary cilium is re-expressed, giving rise to greater tumor aggressiveness." (PMID 32194829, 2020). "It is generally accepted that HK2 has a dual role in tumor cells that HK2 could not only result in cell growth via enhanced glycolysis but also inhibit apoptosis via binding of VDAC-1 to the mitochondrial outer membrane." (PMID 33425771, 2020). "Thus, we can link the si-VDAC1-induced reprograming of the tumor to changes in the interactions between metabolism and the regulation of cell-specific transcriptional networks mediated by an epigenetics program." (PMID 32331482, 2020). "Thus, the changes in chromatin remodelers observed after depletion of VDAC1 is predicted to have a dramatic effect on cellular transcription, as reflected by the altered expression of over 5000 genes and tumor reprograming and growth inhibition." (PMID 32331482, 2020). "Moreover, we analyzed the relationships of KMT2A/VDAC1 expression with different clinicopathologic variables, and found that the expression of KMT2A and VDAC1 was significantly correlated with the tumor type." (PMID 32436862, 2020). "The findings suggest that the VDAC1 is involved in tumour progression and that it may serve as useful biomarker and therapeutic target." (PMID 33053689, 2020). "Thus, the decrease in CD47 levels upon VDAC1 depletion would be expected to enhance anti-tumor immunity." (PMID 31661894, 2019).
tumor (continued). "Here, we asked whether such tumor reprograming is dependent on the duration of treatment with si-RNA specific to human VDAC1 (si-hVDAC1)." (PMID 31661894, 2019). "Previously, we demonstrated that VDAC1 depletion in GBM using si-RNA resulted in inhibited tumor growth involving rewired metabolic properties and inhibited cell proliferation, EMT, invasion, angiogenesis, and stemness, leading to the appearance of neuronal-like cells." (PMID 31661894, 2019). "Indeed, VDAC1 silencing in U-87MG-derived tumors resulted in tumor cell differentiation into astrocyte- and neuron-like cells." (PMID 31195298, 2019). "In addition, complex formation between Ca2+-transport proteins like IP3Rs and VDAC1 at the MAMs and tumor suppressors or oncogenes influences ER–mitochondrial Ca2+ transfer." (PMID 29491433, 2018). "Consequently, in tumor cells with elevated levels of HK bound to VDAC1, apoptosis is suppressed and proliferation is facilitated." (PMID 28713289, 2017). "The high levels of ATP may contribute to stabilizing the tertiary structure of VDAC1, while shielding from pro-apoptotic factor binding, thus protecting tumor cells in a synergic way from PCD." (PMID 28524096, 2017). "Thus, a comprehensive understanding of the exact molecular basis of the complex signaling networks activated by VDAC1 over- or downregulation in the tumor that forms a pro- or anti-tumorigenic milieu is required." (PMID 28824871, 2017). "In addition, tumor progression and sensitivity to chemotherapy was correlated with VDAC1 expression." (PMID 28824871, 2017). "We identified a novel regulatory mechanism between miR-320a and VDAC1, and miR-320a may serve as a tumor suppressor gene and a promising therapeutic target of NSCLCs." (PMID 27304056, 2016). "However, we showed that VDAC1 was over-expressed in lung adenocarcinomas tumor tissue from 44 patients." (PMID 27625993, 2016). "Importantly, we showed that ectopic overexpression of miR-320a blocked tumor cell proliferation and invasion, both in vitro and in vivo, through inhibiting VDAC1." (PMID 27304056, 2016). "Furthermore, we found MiR-320a was significantly decreased in NSCLC tissues versus adjacent non-tumor tissues, and its expression is negatively correlated with VDAC1 in NSCLC tissues by Pearson's correlation coefficient analysis." (PMID 27304056, 2016). "Conversely, high levels of VDAC1 expression may endow tumor cells with a selection advantage by facilitating energy dependent processes such as proliferation and invasiveness." (PMID 27304056, 2016). "Indeed, accumulation of ROS in Vdac1−/− RAS MEF-derived tumors triggered HIF-1α stabilization, abnormal vasculature, and leakage of red blood cells, thus generating an inflammatory response that resulted on a strong impact on VDAC1 tumor development." (PMID 27625993, 2016). "Masson’s trichome staining showed a massive leak of red blood cells from blood vessels into the tumor tissue of the Vdac1−/− RAS MEF and more hemoglobine in the tumor, suggesting that the leak came from partial vascular remodeling, probably coupled with enhanced permeability." (PMID 26322231, 2015). "Finally, we show that knockout of Vdac1 in MEF expressing oncogenic RAS potentiates tumor development in mice by promoting metabolic reprogramming, accelerating vascular destabilization and inflammation." (PMID 26322231, 2015). "Conversely, high levels of VDAC1 expression levels may confer tumour cell selection advantage by facilitating energy dependent processes such as proliferation and invasiveness." (PMID 21297950, 2011). "Thus, VDAC1-derived peptide anti-CSCs can also account for their high efficacy against tumor cells." (PMID 39334905, 2024). "Interestingly, silencing VDAC1 expression has been shown to induce inhibition of tumor growth." (PMID 28713289, 2017). "Altering VDAC-1 levels may lead to opposite effects in tumour cells." (PMID 27936075, 2016).
tumor (continued). "Moreover, after dissection of the various mechanisms involved, our results showed a strong impact of VDAC1 on tumor development, through alterations in the inflammatory response as a result of an abnormal vasculature due to ROS production and HIF-1α stabilization." (PMID 27625993, 2016). "Another possible role for VDAC1 may exist in tumor microenvironments, which are often hypoxic." (PMID 26090338, 2015). "The expressionof BCL2, which is decreased in tumor hepatocytes, canbe suppressed by four proteins (CDK1, VDAC1, MMP9,CYC), the expression of which is increased in malignant hepatocytes compared with hepatocytes from healthy livertissue." (PMID 41541554, 2025). "We noted that VDAC1 was expressed in epithelial cells and macrophages in LUAD and NSCLC scRNA-seq datasets, with a significant positive correlation with tumor stage." (PMID 40052442, 2025). "Six key genes were located within malignant tumor cells and enriched predominantly in the cytoplasm of tumor cells, including PERP, BAK1, VDAC1, FOXO3, AKT3, and IGF1." (PMID 36900213, 2023). "VDAC1 and GRP78 have been identified as receptors for PK5 to mediate anti-angiogenesis by down-regulating HIF-1α/VEGF, and induce tumor cell apoptosis in hypoxic condition." (PMID 36793021, 2023). "For example, in tumor cells and in placental trophoblasts from patients with recurrent miscarriages, the increase of EPB41L4A-AS1 lnc-RNA induced the enhancement of VDAC1 promoter activity affecting histone modification." (PMID 37344914, 2023). "Consistently, in those B16F10 tumor-bearing Jα18-/- chimeric mice, α-GC induced less IFN-γ and IL-4 production in intratumoral CD45.2+Vdac1+/- iNKT cells, despite their normal granzyme B production." (PMID 36741382, 2022). "Across all tumor sections, EPOR expression predicted VDAC1 expression (Pearson’s r = 0.515, p<0.0001)." (PMID 36052260, 2022). "Genes and proteins regulating the TCA cycle (PDHA1, SUCLG2, SUCLG1, and IDH2) as well as mitochondrial function (VDAC1, MRPS31, LARS2, OPA1, and MTIF2) showed higher transcripts and protein levels in Wnt‐high compared with Wnt‐low tumor entities." (PMID 35904277, 2022). "In addition, we found that the expression of VDAC1 was higher in many types of tumor tissues than that in corresponding normal tissues, which was consistent with previous studies and suggested that VDAC1 might act as an oncogene that is related to tumorigenesis and tumor progression." (PMID 35729567, 2022). "Further validation of PPARG’s effect on this pathway was established through immunoblot of tumour lysates probing for PPARG, AKT3, PGC1α, CRM1 and VDAC1." (PMID 33654198, 2021). "By contrast, knockout of VDAC1 in mouse embryonic fibroblasts (MEF) expressing oncogenic RAS, favors tumor development in mice by promoting metabolic reprogramming." (PMID 34658929, 2021). "Tumours derived from clone OE19 showed elevated AKT3, PGC1a and VDAC1 confirming the effect of PPARG on this pathway." (PMID 33654198, 2021). "By investigating the molecular mechanisms by which CTB exerted anti‐tumour effects by targeting mitochondria, we discovered that CTB repressed glycolysis in HCC cells, and induced HK2 dissociation from the mitochondria via VDAC1 and mPTP opening." (PMID 31994339, 2020). "It was previously reported that specific interactions between HSP90 and CYPD, VDAC1 and ANT, and HSPD1 and CypD in mitochondria directly contribute to survival of tumor cells." (PMID 32235444, 2020). "These experiments showed that VDAC1 depletion or IACS-010759 treatment significantly affected cell proliferation in vitro and tumor growth in vivo." (PMID 32792483, 2020). "In this study, we used siRNA specific to human VDAC1 for treating GBM-, lung- and breast-derived subcutaneous tumours." (PMID 30544833, 2018). "Recently, a C-terminal end truncated form of VDAC1, called VDAC1-ΔC, with an apparent molecular weight of 25 kDa on SDS-PAGE under reducing conditions, was detected in tumor cells grown under oxygen-deprived conditions." (PMID 29596470, 2018).
tumor (continued). "In sub-cutaneous and intracranial xenograft mouse models of GBM, the VDAC1-based peptides, N-Ter and Tf-D-LP4, were found to disrupt cell metabolism and energy homeostasis to inhibit tumor growth, invasion, stemness, and induce apoptosis." (PMID 28824871, 2017). "Most of the tumors derived from Vdac1−/− RAS MEF reached a size of 1 cm3 within 27 days of injection, whereas Wt RAS MEF-derived tumors reached this size within 41–43 days and the tumor weights were similar." (PMID 26322231, 2015). "A 2-fold increase in VDAC1 expression was noted in primary HCC tumor tissues compared with adjacent nontumor tissues, highlighting its strong association with HCC." (PMID 39627451, 2024). "This decreased VDAC1 expression in OED and OSCC tissues is an early event and may be a component of the tumor cells’ mechanism for escaping apoptosis." (PMID 37046443, 2023). "By the direct coupling of ATP from mitochondria to glucose uptake via VDAC1-bound HK, mitochondria regulate glycolytic flux via the TCA cycle and ATP synthase, thereby delivering adequate energy and metabolite precursors to tumor cells to meet biochemical requirements." (PMID 35972052, 2022). "In MEFs and canine tumor cell lines, TSPO formed a complex with VDAC, protein kinase A (PKA), and ACBD3 in which VDAC1 function was dependent upon TSPO-regulated phosphorylation of VDAC1 by PKA." (PMID 34191248, 2021). "In group A, VDAC1-ΔC and LGMN were present in tumor (T) tissues, except for patients #7 and #12." (PMID 32194829, 2020). "In contrast, group B showed no VDAC1-ΔC in tumor (T) tissues in parallel with weak or absent expression of LGMN." (PMID 32194829, 2020). "Fourteen out of 19 (73.7%) were classified with high VDAC1 expression and the presence of VDAC1-ΔC in tumor tissues (defined as group A) whereas five out of 19 (26.3%) were classified with a low level of VDAC1 and the absence of VDAC1-ΔC (defined as group B)." (PMID 32194829, 2020). "A significant inverse correlation was found between VDAC1 expression and UICC tumor stage." (PMID 31167495, 2019). "We found that VDAC1, one major protein of the VDAC protein family, may act as a tumor promoter in cervical cancer, and thus may be a novel target for the prevention and treatment of cervical carcinoma." (PMID 27419626, 2016). "We recently reported the presence in tumor cells of a novel hypoxia-induced form of VDAC1 lacking the C-terminus (VDAC1-ΔC)." (PMID 26322231, 2015). "VDAC1 supports their metabolism via the transfer of diverse metabolites and mitochondrial ATP binding, resulting in mitochondrial regulation of glycolytic flow through the TCA cycle and the action of ATP synthase to meet tumor demand for metabolites or metabolite precursors." (PMID 36750173, 2023). "Studies showed that functional EPO receptor signaling was critical for the tumor-promoting growth effects of EPO through in vitro and in vivo experiments, indicating that EPOR expression was positively correlated with the expression of the mitochondrial marker VDAC1 in human NSCLC patient biopsies." (PMID 37746281, 2023). "Therefore, overexpression of VDAC1 did not promote the release of apoptotic factors but increased the energy supply of glycolysis, which was beneficial to tumor cells." (PMID 35958281, 2022). "Notably, in tumor explants from the LSAA/HPUFA group, the same ETC subunits were found to be increased along with VDAC1, arguing that lipid peroxidation could at least in part be ascribed to increased mitochondrial mass and ETC-derived mitochondrial ROS." (PMID 36613691, 2022). "Overexpression of the last eight aa of HKDC1 at the C-terminal (HKC8) truncates significantly suppresses tumor growth and results in dissociation of HKDC1 from vascular endothelial growth factor 1 (VDAC1), indicating that HKC8 may be a novel antitumor target for ENKTL treatment." (PMID 32203147, 2020).